THAP2 (THAP domain containing 2)
Synonyms: DKFZP564I0422
Tractability: PROTAC: ubiquitination databases record sites on it.
Gene: Protein-coding gene on chromosome 12 (71,664,301 to 71,680,644, forward strand). Ensembl gene ENSG00000173451.
Subcellular location (Human Protein Atlas): Golgi apparatus; Nucleoplasm
Gene Ontology:
Cellular component: nucleolus; nucleus
Genetic constraint (gnomAD): Loss-of-function variants: 16 observed, 21.37 expected, observed/expected ratio (o/e) 0.75, 90% interval 0.51 to 1.14. The upper end of that interval is the gene's LOEUF score, 1.14, which puts it in group 4 of 6, group 1 being the genes least tolerant of losing a copy. Missense variants: 251 observed, 275.86 expected, observed/expected ratio (o/e) 0.91, 90% interval 0.82 to 1.01. Synonymous variants: 80 observed, 94.39 expected, observed/expected ratio (o/e) 0.85, 90% interval 0.71 to 1.02.
Homologues: Orthologues: chimpanzee THAP2 (100% identical), macaque THAP2 (98% identical), dog THAP2 (89% identical), guinea pig THAP2 (88% identical), pig THAP2 (88% identical), mouse Thap2 (84% identical), rat Thap2 (75% identical), zebrafish zgc:153292 (24% identical), zebrafish zgc:163143 (23% identical), Drosophila melanogaster CG13894 (10% identical). Paralogues in human: THAP1 (30% identical), THAP3 (23% identical), THAP7 (23% identical), THAP8 (19% identical), ARL14EP (10% identical), THAP6 (10% identical), ARL14EPL (6% identical).
Diseases named in the same sentence as THAP2 in open-access papers:
THAP2 is named in the same sentence as 3 diseases in open-access papers, as found by Europe PMC text mining. Sharing a sentence is not in itself a finding about the gene and the disease. The quoted sentences say what the papers report.
tumor (2 papers, 2014 to 2024). "In this context, miR-100 would act as an oncomiR because it downregulates THAP2, a putative tumor suppression protein that is important for Rb function, apoptosis induction and DNA chromatin remodeling." (PMID 25493074, 2014). "However, they significantly differed in terms of marker genes (AKR1C1, FOSL1, LIF, and THAP2 vs. WNT5A, GREM1, TNC, and MMP1), tissue origins (normal vs. tumor), and organ preferences." (PMID 38744958, 2024).
THAP2 also shares sentences with these, for which no sentence is quoted: bladder cancer (1 paper); cancer (1).